EPCAM (epithelial cell adhesion molecule)
Diseases named in the same sentence as EPCAM in open-access papers (continued):
Sharing a sentence is not in itself a finding about the gene and the disease.
Papillary Craniopharyngioma (1 paper, 2019). A craniopharyngioma composed of sheets of squamous epithelium which separate to form pseudopapillae. "Moreover, EpCAM (CD326), which showed higher levels in AC compared to papillary craniopharyngioma and RCC, was identified in four of them." (PMID 31191748, 2019).
pituitary tumor (1 paper, 2022). A benign or malignant neoplasm affecting the pituitary gland. "In specimens from patients with pituitary tumors, EpCAM immunostaining was found within the normal anterior pituitary and predominantly located at the cell membrane of endocrine cells." (PMID 35903276, 2022).
placenta previa (1 paper, 2021). "Here, NanoVelcro Chips pre-coated with anti-EpCAM were utilized to isolate and enumerate cTBs in pregnant women with normal placentation (n = 2), placenta previa (n = 3), and PAS (n = 5)." (PMID 34344888, 2021).
prostatic intraepithelial neoplasia (1 paper, 2014). "Moreover, our findings support the previous observation that, in prostate tissue, EpCAM expression significantly increases from normal tissue via prostatic intraepithelial neoplasia to adenocarcinoma." (PMID 25593983, 2014).
rectosigmoid carcinoma (1 paper, 2021). A malignant epithelial neoplasm that arises from the rectosigmoid area and invades through the muscularis mucosa into the submucosa. "An ongoing phase I clinical dose escalation and optimization trial explores the intraoperative use of an EpCAM-specific fluorescence agent in esophageal, gastric, and rectosigmoid cancer (Netherlands Trial Register, ID NL7363)." (PMID 33799475, 2021).
relapsing (1 paper, 2015). "Importantly, in relapsing tumors, the CD44+ cell volume expands, and CD133+ and EpCAM+ cells proportionally proliferate, indicating that the CD44+ cell population is heterogeneous within primary PDACs and relapsing tumors." (PMID 25797268, 2015).
salivary gland neoplasm (1 paper, 2023). Tumors of the SALIVARY GLANDS. "The purpose of this research is to study the expression patterns of EpCAM in malignant salivary gland neoplasms and to explore its potential association with tumor characteristics, clinical outcomes, and therapeutic response." (PMID 37627911, 2023). "Few studies in the literature have investigated the expression of EpCAM in salivary gland neoplasms and the correlation of histopathologic findings with the biological behavior of these tumors." (PMID 37627911, 2023). "In this study, we report the differential expression of EpCAM in eight types of malignant salivary gland neoplasms and the relationship between the clinical and histopathologic features of these tumors and the degree of expression." (PMID 37627911, 2023). "They included EpCAM and showed different expression patterns of EpCAM among salivary gland neoplasms." (PMID 37627911, 2023). "Therefore, the aim of this study was to investigate the expression of EpCAM in malignant salivary gland neoplasms and its relationship with their biological behavior." (PMID 37627911, 2023). "Therefore, studying the role of EpCAM in malignant salivary gland neoplasms and its correlation with the biological behavior of these tumors may provide valuable insights into their pathogenesis." (PMID 37627911, 2023).
sarcomatoid carcinoma (1 paper, 2017). A malignant epithelial neoplasm characterized by the presence of spindle cells and anaplastic morphologic features. "It showed co-expression of Vimentin, CK7, D2–40, focal PanCK, but it stained negatively for EMA, CEA, EpCAM, usually positive in sarcomatoid carcinoma." (PMID 28810922, 2017).
sellar tumours (1 paper, 2016). "In summary, EpCAM shows different expression patterns in CP subtypes and RCC, and may, therefore, be used as an additional diagnostic tool in the sometimes challenging differential diagnosis of sellar tumours." (PMID 27431859, 2016).
squamous intraepithelial lesions (1 paper, 2017). "EpCAM expression was also investigated on specimens with precancerous lesions of the uterine cervix, including high-grade (HSIL) and low-grade (LSIL) squamous intraepithelial lesions." (PMID 29202724, 2017).
Stroke (1 paper, 2016). Sudden impairment of blood flow to a part of the brain due to occlusion or rupture of an artery to the brain. "Therefore, it is possible that this increase of the pan epithelial marker EpCAM in the stroke control group may be related to stroke per se." (PMID 27427978, 2016).
thyroid nodule (1 paper, 2016). A small circumscribed mass in the THYROID GLAND that can be of neoplastic growth or non-neoplastic abnormality. "The presence of CD147+EpCAM+ taMPs were specific to tumour-bearing patients thus allowing the specific distinction of malignancies from patients with thyroid nodules." (PMID 27127176, 2016). "Increased level of EpCAM single positive MPs were, in turn, also detected in patients with thyroid nodules." (PMID 27127176, 2016). "Surprisingly, EpCAM+ taMPs were also found elevated in thyroid nodules patients (short: struma, n = 40) as compared to healthy controls by 1.9 fold (p < 0.05)." (PMID 27127176, 2016). "However, certain disease/health circumstances associated with epithelial damage such as struma nodosa (thyroid nodules) does not permit to draw conclusions only on EpCAM taMPs." (PMID 27127176, 2016). "Additionally, the calculated overall positive (PPV) and negative predictive values (NPV) across the investigated cancer entities (NSCLC, CRC and PaCa) for EpCAM+CD147+ taMPs distinguishing CRC and other neoplasia from healthy controls and from thyroid nodules (struma nodosa)." (PMID 27127176, 2016).
thyroid tumor (1 paper, 2021). A benign or malignant neoplasm affecting the thyroid gland. "Because advanced thyroid tumors often demonstrate loss of epithelial markers, we hypothesized that lack of EpCAM expression is due to de-differentiation of the tumors from which these cell lines were derived rather than an artifact of cell culture." (PMID 33806425, 2021).
urothelial neoplasm (1 paper, 2023). A neoplasm involving a urothelium. "Despite of a progressive loss of TROP2/EpCAM during tumor cell dedifferentiation in pTa tumors, the lack of associations with clinicopathological parameters in pT2-4 cancer argues against a major cancer driving role of both proteins for the progression of urothelial neoplasms." (PMID 38282671, 2023). "In summary, our data show that TROP2 and EpCAM expression is common and highly interrelated in urothelial neoplasms." (PMID 38282671, 2023). "Our data show that TROP2 and EpCAM expression is common and highly interrelated in urothelial neoplasms." (PMID 38282671, 2023). "Although TROP2 and EpCAM are both highly expressed in most urothelial neoplasms, the level of expression might be relevant." (PMID 38282671, 2023).
uterine tumors (1 paper, 2020). "Positive EpCAM staining was demonstrated in both uterine tumors and metastases by IHC." (PMID 32041116, 2020). "Conjugation of EpCAM to the near-infrared fluorophore Alexa680 yielded EpCAM-AF680, and its application as an optical imaging contrast reagent was found to faithfully depict uterine tumors and metastases in both cell line derived and PDX mouse models." (PMID 32041116, 2020).
xerostomia (1 paper, 2019). Dryness of the mouth resulting from reduced salivary secretion. "In fact, the IHC scores of subcellular EpEX or EpICD were not only related to the histopathological grade of LSG but also associated with some characteristics of pSS patients such as age, disease duration, xerostomia, and anti-Ro/SSA, which suggested the close connection between EpCAM and pSS." (PMID 31886299, 2019). "The features of samples including gender, disease duration, xerostomia, saprodontia, anti-Ro/SSA, ANA, ANA and RF double positive, and anti-Ro52, which have been demonstrated to relate to pSS, were enrolled in multiple logistic regression, together with IHC scores of subcellular EpCAM." (PMID 31886299, 2019).
tumor (2,540 papers, 1987 to 2026). "Epithelial cell adhesion molecule (EpCAM) is a tumor-associated antigen that marks pluripotent embryonic stem cells (ESCs)." (PMID 41963283, 2026). "Epithelial cell adhesion molecule (EpCAM), a transmembrane glycoprotein involved in tumour proliferation and signalling pathways, has been implicated in the pathogenesis across multiple epithelial malignancies." (PMID 42164196, 2026). "The PDX257S cell line demonstrated faster tumor growth, higher expression of human epithelial cell adhesion molecule, increased mutation burden in BC‐associated genes, and significant alterations in BC‐related gene expression, compared to the original tumor." (PMID 40801146, 2025). "A study in a similar Guangxi cohort demonstrated that the infection is associated with increased expression of HCC stem cell markers CK19 and EpCAM, which are linked to aggressive tumor biology and poor prognosis." (PMID 40906786, 2025). "The increase in EPCAM in the plasma and tumor tissues was confirmed by enzyme-linked immunosorbent assay and immunohistochemistry analyses, respectively." (PMID 41551611, 2025). "Epithelial cell adhesion molecule (EpCAM), a marker of liver progenitor cells, was associated with aggressive tumor behavior and poor prognosis." (PMID 41042332, 2025). "In contrast, EpCAM expression was markedly reduced in higher-stage tumors, indicating a possible loss of epithelial characteristics during tumor advancement." (PMID 40806559, 2025). "This type of membranes contains a unique profile of tumor-associated antigens (TAAs) and adhesion proteins (e.g., EpCAM, integrins) that serve as a tumor-specific “identification signature”." (PMID 41374968, 2025). "Many techniques were applied to alleviate the on-target off-tumor toxicities associated with targeting EpCAM." (PMID 40057807, 2025). "Positive enrichment targets tumor‐associated antigens, with epithelial cell adhesion molecule (EpCAM) being a preferred biomarker for identifying CTCs in epithelial‐originated malignancies." (PMID 40437761, 2025). "EpCAM is a common tumor-associated antigen for the development of CAR T based cell therapies, and hence, the IFP-induced downregulation of this molecule would impair the recognition of engineered cells." (PMID 40969762, 2025). "Further, epithelial tumour cells are marked by epithelial cell adhesion molecule (EpCAM), and it has been linked to prognosis and chemoresistance." (PMID 41514600, 2025). "The analysis of tumor-associated transcripts showed that both M1 and M2 conditioned medium induced high levels of EPCAM mRNA and significantly decreased the expression of MYC, an epithelial-to-mesenchymal transition marker, in SCC cell lines." (PMID 41259557, 2025). "Our results demonstrated the high sensitivity and specificity of EpCAM for detecting tumor cells, supporting its integration as a valuable diagnostic tool." (PMID 40525275, 2025). "EpCAM is now recognized as one of the most studied tumor-associated antigens and has developed into a well-established marker for epithelial cells utilized in pathological examinations of various cancers." (PMID 40778224, 2025). "For instance, in non-small cell lung cancer, EpCAM expression helps identify minor cell populations with self-renewal and tumor-forming capabilities, which are linked to tumor recurrence and metastasis." (PMID 39184916, 2024).
tumor (continued). "Next, we established control and ATX-deficient tumors, sorted EpCAM+ tumor cells by fluorescence-activated cell sorting (FACS) and measured Ccl11 expression, which was higher in ATX-deficient PDAC cells." (PMID 38195933, 2024). "Beyond its initial identification as a tumor-associated antigen, EpCAM has emerged as a key player in tumor development, acting as a signaling receptor and activator of the Wnt pathway, which is involved in cell proliferation, migration, and invasiveness." (PMID 39595576, 2024). "TACSTD2 and EpCAM were previously reported to be associated with cell adhesion and metastasis of tumor, implying the effect on recurrent MPE accompanied with CLDN4." (PMID 38629624, 2024). "Epithelial cell adhesion molecule (EpCAM or CD326) is an overexpressed surface receptor known as a tumor-associated antigen for CRC cells especially tumor-initiating cells (primitive stem cell-like)." (PMID 38561432, 2024). "As expected, according to our non-EpCAM-based detection method, higher numbers of candidate CTCs were detected and isolated as single cells whose tumour origin was confirmed by mutational and low-pass whole-genome sequencing." (PMID 38177660, 2024). "Higher levels of EpCAM‐positive EVs are thus interpreted as reflecting increased tumour burden, and consequently, negatively associated with patient survival across various cancers." (PMID 38490958, 2024). "The expression of EpCAM antigen is associated with the proliferation and metastasis of tumour cells." (PMID 39107717, 2024). "EpCAM is therefore an attractive, tumor-associated antigen for tumor targeting of these cancers for which a targeted therapeutic approach is highly desirable." (PMID 39513807, 2024). "Other possible strategies include the analysis of circulating ensembles of tumor-associated cells (C-ETACs), defined as clusters of pan-cytokeratin and EpCAM-positive cells (at least three)." (PMID 38539525, 2024). "Despite being the key and effective therapeutics for human cancer, monoclonal antibodies (mAbs) against the tumor-associated antigen EpCAM have shown a limited clinical benefit that prevented their broader use in the clinic." (PMID 39595576, 2024). "Increased EpCAM-levels are typical of epithelium-derived tumors, and EpCAM overexpression in tumor tissue has been associated with poor prognosis in different carcinomas." (PMID 38928484, 2024). "Due to shared expression on the surface of tumor cells and healthy tissue, the risk of on-target-off-tumor reactions is significantly increased in the context auf EpCAM-directed CAR T-cell and anti-PD-1 treatment." (PMID 39358663, 2024). "High EpCAM expression, however, has been described as an epithelial marker associated with cancer stemness and tumor initiation capacity." (PMID 39439549, 2024). "Studies that used antibodies against EpCAM’s intracellular domain suggested that this cytoplasmic staining actually reflects tumor aggressiveness and is associated with prognosis." (PMID 38928484, 2024). "In colorectal cancer, EpCAM expression levels are associated with tumor aggressiveness, disease progression, and poor prognosis." (PMID 39184916, 2024). "EpCAM is an attractive target for targeted therapies as it is highly expressed on cancer cells and has been implicated in tumor growth." (PMID 39513807, 2024). "EpCAM is a pan-epithelial differentiation carcinoma-associated antigen that has been reported to be up-regulated in rapidly proliferating tumor cells in most human epithelial carcinomas." (PMID 37941056, 2023). "Declining levels of expression for both proteins with increasing tumor grade is consistent with a progressive loss of TROP2/EpCAM during tumor cell dedifferentiation." (PMID 38282671, 2023).
tumor (continued). "There was a significant association between EpCAM and E-cadherin expression in these tumour cells (p =0.035)." (PMID 37533952, 2023). "One study evaluating several surface markers expressed on extracellular vesicles (EV) showed that AnexinV + EpCAM + tumor-associated microparticles precisely diagnosed tumor nodules between 1 and 2 cm as HCC; the smallest detected nodule was 11 mm in diameter." (PMID 37626820, 2023). "The strong association of EpCAM expression with high-grade tumors suggests a possible role in tumor progression, making EpCAM a potential target for antibody-mediated therapy." (PMID 37016296, 2023). "The objective of this study was to evaluate a composite biomarker of EpCAM-positive circulating tumor cells and serum AFP to identify patients at high risk of early recurrence within 2 years after liver resection." (PMID 38012205, 2023). "For diagnostic purposes, differential EpCAM expression, alone or in combination with other markers, can help differentiate several neoplasms with overlapping histopathologic features." (PMID 37627911, 2023). "Aberrant EpCAM expression has been associated with tumor initiation, progression, metastasis, and resistance to therapy in several malignancies." (PMID 37627911, 2023). "The negative enrichment of CD45− cells combined with a quantitative real-time PCR-based platform showed that EpCAM mRNA+ in HCC patients (n = 56) before TACE is associated with a higher risk of tumor progression." (PMID 36768881, 2023). "Epithelial cell adhesion molecule (EpCAM) is a tumor-associated antigen that is frequently overexpressed in various carcinomas." (PMID 38067255, 2023). "Epithelial cell adhesion molecule (EpCAM) is a type I transmembrane glycoprotein that was once thought to be a tumor-associated antigen due to its high expression in quickly growing epithelial malignancies." (PMID 36990999, 2023). "The expression of EpCAM was demonstrated to be increased in the tumours of chemo-resistant patients and associated with unfavourable outcomes." (PMID 38201468, 2023). "Epithelial cell adhesion molecule (EpCAM), human epidermal growth factor receptor 2, folic acid receptor, and transferrin receptor are among the most extensively explored tumour-associated cell-surface antigens for immunomagnetic separation of CTCs." (PMID 37533950, 2023). "We compared the effector functions and cytotoxicity of these CAR-T cell variants against a group of tumor cell lines with a wide range of EpCAM expression as well as human primary epithelial cells (EpC)." (PMID 37045815, 2023). "Expression of VIM on tumor cells with partial or complete loss of epithelial marker expression such as EpCAM represents hybrid or full EMT status." (PMID 37789961, 2023). "CTCs express tumor-associated cell surface antigens (e.g., EpCAM and CKs) that set them apart from other blood cells (i.e., positive immunoselection)." (PMID 38001632, 2023). "We successfully tested the tool for quantification of EVs harboring common EV markers, namely, CD9 and CD81, and a tumor-associated biomarker EpCAM." (PMID 35564289, 2022). "Multiple single epithelial cell adhesion molecule (EpCAM)-positive CTCs were recovered by DEPArray in five patients with ≥100 CTCs and compared with matched cfDNA and primary tumor tissue using targeted NGS of about 2200 mutations in 50 cancer genes." (PMID 35887191, 2022). "High EPCAM expression is often associated with poor prognosis and is linked to tumor cell proliferation and metastasis." (PMID 35730316, 2022). "Our analysis showed a significant positive association of EpCAM expression with tumor size (P = 0.02), tumor stage (P = 0.007), tumor differentiate (P = 0.005), vascular (P = 0.01), neural (P = 0.01), and lymph node (P = 0.001) invasion." (PMID 35016698, 2022). "Of note, one of the ideal tumor-associated antigens (TAA) that is expressed during hypoxia is the epithelial cell adhesion molecule (EpCAM)." (PMID 36424577, 2022).